ENSG00000285589 (novel transcript)
Gene: Protein-coding gene on chromosome 19 (12,668,071 to 12,681,834, reverse strand). Ensembl gene ENSG00000285589.
Genetic constraint (gnomAD): Missense variants: 221 observed, 202.8 expected, observed/expected ratio (o/e) 1.09, 90% interval 0.98 to 1.22. Synonymous variants: 104 observed, 84.71 expected, observed/expected ratio (o/e) 1.23, 90% interval 1.05 to 1.45.